MMP2 (matrix metallopeptidase 2)
Diseases named in the same sentence as MMP2 in open-access papers (continued):
Sharing a sentence is not in itself a finding about the gene and the disease.
Hyperglycemia (40 papers, 2009 to 2026). An increased concentration of glucose in the blood. "Biochemical and metabolic analysis consistently revealed that Mmp2 deficiency suppressed Akh release, decreased tobi expression, as well as abolished lipid loss and hyperglycemia (h‒i)." (PMID 39924534, 2025). "MMP-2 downregulated activity occurred under hyperglycemia and this profile of activation was accompanied by the translocation of intracellular N-terminal truncated isoform of MMP-2 (NT-MMP-2) from mitochondria-associated membrane (MAM) into mitochondria." (PMID 33050121, 2020). "Our results are consistent with previous reports showing that hyperglycemia is associated with increased plasma concentration of MMP-2." (PMID 28770228, 2017). "In the present study, HbA1c was the only factor associated with free TGF-β2 levels (as a measurement of MMP2 activity), suggesting that hyperglycemia may affect TGF-β2 cleavage." (PMID 39653743, 2024). "In addition, the investigators looked at the potential regulatory mechanisms of this compound in murine bEnd3 cerebral endothelial cells, where they detected some downregulatory effects on specific matrix metalloproteinases (MMP-2) associated with hyperglycemia." (PMID 36079821, 2022). "As previously shown by our group, hyperglycemia decreases the expression of metalloproteinases, such as MMP2 and MMP9, which in the pancreas directly participate in the migration process of endocrine cell precursors through the degradation of ECM." (PMID 40563978, 2025). "Here we showed a dual effect of hyperglycemia reduced MMP2 activity on TGF-β2 levels and collagen in T2D plaques: affecting smooth muscle cell migration, TGF-β cleavage and thereby limiting VSMC differentiation." (PMID 39653743, 2024). "Here, we show that T2D plaques have smaller fibrous caps due to hyperglycemia-dependent reduction of MMP2 activity, affecting synthetic vascular smooth muscle migration and TGF-β2 cleavage, which in turn limits VSMC differentiation and collagen formation." (PMID 39653743, 2024). "Nevertheless, previous studies have shown that the increase of MMP2 and MMP9 activities is associated with the inflammatory process and oxidative stress in APP/PS1 mice and hyperglycemia alters the PKC-β pathway, causing an increase in MMP2." (PMID 36345028, 2022). "Obese EV display reduced content of VEGF, MMP-2, and miR-126 and show impaired angiogenic potential compared with normal EV under hyperglycaemia." (PMID 33477341, 2021). "At this early stage of stroke, hyperglycemia also causes BBB disruption, again mediated by MMP-2/9 extracellular degradation, caveolin-1-mediated intracellular translocation, and autophagy-lysosome-mediated degradation of ZO-1 protein." (PMID 33362697, 2020). "PECAM-1 has been described to be degraded by matrix metalloproteinase-2 (MMP-2), an enzyme found to be upregulated by hyperglycemia." (PMID 32964051, 2020). "The present study is valuable because it defines the anatomical location (cortex vs. medulla) and the time of induction of MMP-2 isoform induction by hyperglycemia in both type 1 and type 2 murine diabetic models." (PMID 30253743, 2018). "This suggests that hyperglycemia affects the physiological production of TIMP-4 following increased MMP-2 synthesis." (PMID 28770228, 2017). "Hyperglycemia increases an expression and activity of MMP-2 and MMP-9 in aortic smooth muscle cells, vascular tissue, and plasma, affecting metabolism of the extracellular matrix." (PMID 28770228, 2017). "Expression and activation of MMP-2 has been demonstrated as a key event in oxidative stress injury to heart and hyperglycaemia promoted BBB dysfunction." (PMID 24755281, 2014). "In conclusion, PPAR-α stimulation prevented the decrease in claudins through a mechanism involving a correction of hyperglycemia, decreasing it in kidney oxidative stress and MMP-2 and MMP-9 activities, showing a promising nephroprotective action in the early stage of DN." (PMID 39684861, 2024).
Hyperglycemia (continued). "Furthermore, ACE2 can reduce myocardial collagen deposition induced by hyperglycaemia and activate MMP2." (PMID 33443816, 2021). "This suggests that DHEA may prevent the development of conditions requiring a healing process, suppress the overexpression of MMP-2 through its anti-inflammatory response, and improve tendon matrix synthesis and turnover, which were enhanced by hyperglycemia." (PMID 34090401, 2021). "The activation of TGF-β1 may include heart damage, the production of reactive oxygen species, AngII, hyperglycemia, pH changes and specific proteases, such as plasmin, matrix metalloproteinase-2 (MMP-2), and MMP-9." (PMID 33321955, 2020). "We hypothesized, in the setting of experimental and clinical diabetic nephropathy, that hyperglycemia-mediated oxidative stress enhances tubular epithelial expression of both MMP-2 isoforms, leading to cellular injury." (PMID 28178341, 2017). "It should be noted that human placental tissue expresses Tie2 receptor and angiopoietins, with inflammatory mediators and hyperglycemia enhancing its release from the feto-placental endothelial cells and trophoblasts via induction of MMP2, MMP9 and MT1-MMP activities." (PMID 24376824, 2013). "Therefore, we determined the individual and combined effect of hyperglycemia and HHcy on MMP-2 and MMP-9." (PMID 20828387, 2010). "Interestingly, hemoglobin A1c (HbA1c) was inversely associated with free TGF-β2 levels, suggesting that hyperglycemia may affect MMP2 activity." (PMID 39653743, 2024). "Downstream, VEGF signaling activates PKC, an enzyme involved in endothelial permeability, then hyperglycemia promotes dysfunction in its pathway, leading to increased NADPH oxidase and MMP2, further promoting cytokine expression and oxidative stress." (PMID 36620773, 2022). "The aim of this work is to better clarify the role of matrix metalloproteinase 2 (MMP-2) isoforms and of translocator protein (TSPO)/voltage-dependent anion-selective channel 1 (VDAC1) modulation in the development of hyperglycaemia-induced myocardial injury." (PMID 33050121, 2020). "Studies suggest that hyperglycemia increases oxidative stress in various cells, leading to an activation of COX-2 which in turn induces a biosynthesis of MMP-2 and MMP-9." (PMID 28770228, 2017). "Our results demonstrate that treatment with rosiglitazone alone is able to improve the hyperglycemia, dyslipidemia, and to decrease TNF-α, TGF-β, collagen-I and collagen-III and increased MMP-2 but within a minimal effect." (PMID 21450068, 2011). "LBP was demonstrated to protect RPE cells against hyperglycemia- and H2O2-induced apoptosis through its antioxidant effect and to downregulate matrix metalloproteinase 2 (MMP2) derived from RPE cells, thereby jointly contributing to the outer BRB stabilization." (PMID 41601904, 2026). "Our previous observation that PMP (when incorporated into CRC cells) stimulate the metalloproteases MMP-2 and MMP-9 (which are able to degrade the extracellular matrix) may be consistent with the findings of studies focusing on hyperglycaemia." (PMID 40713559, 2025). "Previous studies have demonstrated that hyperglycemia induces an alteration in the pattern of podocytes integrin expression, resulting in an enhanced synthesis of COL4 and a reduced expression of matrix metalloproteinases (specifically MMP-2)." (PMID 39932642, 2025). "Hyperglycemia disturbs trophoblast proliferation and invasion via inhibiting the epithelial-mesenchymal transition, altering the protein expression of related proteases (MMP9, MMP2, and uPA) and angiogenic factors (VEGF, PIGF)." (PMID 37091848, 2023). "Plg levels were not affected by hyperglycaemia that, on the contrary, reduced plasmin activity by 1.3‐fold (P < 0.01) and increased MMP‐2/MMP‐9 levels and activity by 2.2‐, 2.4‐ and 2.2‐fold (P < 0.001)." (PMID 30426662, 2019).
Hyperglycemia (continued). "Results showed that the hyperglycemia-induced GAG alterations in the cell surface perlecan as well as in the ECM indeed upregulated the expressions of IL-6, IL-8, and MCP-1 and the activities of MMP-2 and MMP-9 and downregulated the expressions of TIMP-2." (PMID 23983782, 2013). "In this consideration, our study highlights the role of MMP-2 in the regulation of mitochondrial injury mediated by TSPO and VDAC1 in the onset of DCM, thus contributing to the identification of novel potential targets of cardioprotective therapeutic interventions under hyperglycaemia." (PMID 33050121, 2020). "Moreover, in vitro studies show that hyperglycaemia can increase MMP2 activation, whilst BBB disruption induced by advanced glycation end-products (AGEs) produced under hyperglycaemic conditions can be reversed by inhibiting MMP-2 activity." (PMID 27655189, 2016). "However, we did not observe any Cdkn1a or Mmp2 expression in Gcg+ islet cells in non-infiltrated/intact islets of 8-week mice, insulitic islets in 13-19-week old euglycemic NOD mice, or in residual islets of recently diabetic (<1 week after hyperglycemia) 19-20 week NOD mice (n = 3 mice per group)." (PMID 36277717, 2022).
preeclampsia (38 papers, 2009 to 2026). Preeclampsia is a hypertensive disorder of pregnancy that is characterized by new-onset hypertension with proteinuria presenting after 20 weeks of gestation, and depending on mild or severe forms may initially present with severe headache, visual disturbances, and hyperreflexia. "In conditions like preeclampsia, elevated oxidative stress and inflammation further upregulate Mmp2 through cytokines like interleukin-8, linking NO deficiency to increased Mmp2 expression and vascular remodeling." (PMID 39769454, 2024). "Placental ischemia is suggested as the primary trigger of preeclampsia-associated impairments of both endothelium-derived nitric oxide (NO) and the vascular activity of extracellular matrix metalloproteinase-2 (MMP-2)." (PMID 37628999, 2023). "Other research analyzed the relationship between MMP2 polymorphisms (−306C>T and −735C>T) and the response to antihypertensive treatment in a preeclamptic group, patients with gestational hypertension and healthy pregnant women." (PMID 35885543, 2022). "Mmp2 and Mmp9 are the most abundant gelatinases expressed during trophoblast invasion in humans, and reduced expression of Mmp9 is associated with preeclampsia in mice and humans." (PMID 34767447, 2021). "We investigated the association of MMP-9 polymorphism rs3918242 (-1562 C>T) and MMP-2 polymorphism rs2285053 (-735 C>T) with the risk of preeclampsia." (PMID 34208487, 2021). "However, very few studies have investigated the association between MMP-2 polymorphisms and gestational hypertension and PE." (PMID 34208487, 2021). "However, further research into the molecular mechanisms underlying the interactions among NAMPT, TIMP1 and MMP2 and their relationship with the response to antihypertensive therapy in preeclampsia is needed." (PMID 29541029, 2018). "Additionally, Blimp1 regulates expression of matrix metalloproteinase Mmp2, implicated in trophoblast invasion and preeclampsia, though its precise function in the placenta requires clarification." (PMID 28754907, 2017). "Increased activity of MMPs seems to play a role in preeclampsia, as plasma levels of MMP-2 have been found to be elevated in patients with preeclampsia, so SNPs in genes encoding MMPs have been studied as biomarkers of susceptibility to preeclampsia." (PMID 26317342, 2015). "Dysregulation of MMP‐2 and/or MMP‐9 has been implicated in both gestational hypertension and preeclampsia." (PMID 40844502, 2025). "Reduced vascular MMP-2 gelatinase activity and vascular hyper-reactivity have been observed in models of preeclampsia induced by uteroplacental ischemia, which is caused by the reduction of uterine perfusion pressure (RUPP) in rats." (PMID 37628999, 2023). "Decreasing MMP2 and MMP9 impairs spiral artery remodeling and causes initial pathological symptom of preeclampsia during early gestation." (PMID 36910123, 2022). "The abnormal production of matrix metalloproteinases (MMPs), especially MMP-9 and MMP-2, plays a pivotal role in hypertensive disorders of pregnancy, and as such, can influence the development of preeclampsia." (PMID 34208487, 2021). "The MMP2 SNPs: g-1306 C>T (rs243865) and g-735 C>T (rs2285053) were analyzed in the context of both PE and gestational hypertension together with circulating MMP-2 and tissue inhibitor of metalloproteinase (TIMP)-2 levels." (PMID 30618791, 2018). "A recent work demonstrated that miR-93 is elevated in preeclampsia and inhibits MMP-2, reducing migration and invasion of trophoblast cells." (PMID 28726716, 2017). "It has been reported that MMP-2 plasma levels are elevated in preeclampsia, and that this event is mediated by the vascular endothelial growth factor (VEGF), which controls vascular permeability." (PMID 28726716, 2017). "Expression of different MMPs such as MMP-2, -8, -9, and -11 was downregulated in placental tissues from pregnancies complicated with preeclampsia at >35 weeks of gestation compared to normal pregnancies." (PMID 28726716, 2017).
preeclampsia (continued). "In a different study, 14 biomarkers for preeclampsia, including MMP-2 and MMP-9, were evaluated in urine samples." (PMID 28726716, 2017). "We compared the distribution of genotypes for NOS3 G894T, T-786C, and VNTR in intron 4, as well as MMP2 C-1306T and MMP9 C-1562T, and tested their association with preeclampsia and its major complications." (PMID 26317342, 2015). "When subdivided into subgroups, amniotic fluid from women who eventually developed preeclampsia or superimposed preeclampsia showed significantly higher MMP-2 levels than normotensive women (P < 0.05)." (PMID 19698156, 2009). "The invasive nature of the procedure precludes the use of amniotic fluid MMP-2 levels as a screening test for preeclampsia, but rather as a means of gaining further insight into the pathophysiology of the disease." (PMID 19698156, 2009). "This study supports our results of elevated amniotic fluid MMP-2 during the second trimester, prior to clinical presentation of preeclampsia." (PMID 19698156, 2009). "Others found higher total VEGF (vascular endothelial growth factor), MMP-2, and endothelin-1 concentrations in umbilical vein endothelial cells of women with preeclampsia and showed significant positive correlations between them." (PMID 19698156, 2009). "While MMP-2 and MMP-9 are physiologically involved in trophoblast invasion and angiogenesis, and MMP-3 in cervical remodeling, their overexpression has been associated with pregnancy complications such as preeclampsia, infection, and preterm labor." (PMID 41450943, 2025). "The reduction of MMP2 expression in the placentas with preeclampsia (PE) was also observed." (PMID 37143106, 2023). "Genetic polymorphisms in MMP-2 and MMP-9 transcription have been described in preeclampsia." (PMID 36835024, 2023). "The decrease in MMP-2 and MMP-9 activity or ratios of MMP-2/TIMP-2 and MMP-9/TIMP-1 might be involved in the pathogeneses of early pregnancy loss and preeclampsia." (PMID 33796532, 2021). "Furthermore, findings at the 36th gestational week MMP-2 concentrations were elevated in preeclampsia." (PMID 31703340, 2019). "Moreover, our study confirms the observations of other researchers that the promoter polymorphisms of the MMP2 and MMP9 genes exert an insignificant effect on preeclampsia development." (PMID 29670668, 2018). "The aim of the present study was to determine whether the most common MMP1, MMP2, MMP3, and MMP9 gene polymorphisms in maternal and fetal genes are associated with preeclampsia." (PMID 29670668, 2018). "The present study examines whether the occurrence of single-nucleotide polymorphisms (SNP) in the MMP1, MMP2, MMP3, and MMP9 genes is related to the outcome of preeclampsia." (PMID 29670668, 2018). "MMP-2 levels are increased in the circulation of women who later developed preeclampsia." (PMID 30383759, 2018). "In fact, the same investigators found that higher net activity of MMP-9, but not MMP-2, was associated with gestational hypertension, however this trend in MMP activity was absent in PE." (PMID 28143958, 2017). "Furthermore, MMP-2 elevation can be detected from the second trimester onwards in the plasma of women who subsequently develop preeclampsia." (PMID 28726716, 2017). "Higher levels of MMP-2 have been demonstrated in plasma of women with preeclampsia." (PMID 19698156, 2009). "Several other studies have found increased plasma MMP-2 levels in women with preeclampsia." (PMID 19698156, 2009). "More recent studies have shown altered serum MMP-2 levels prior to the onset of preeclampsia." (PMID 19698156, 2009). "This significantly higher concentration of PLAC1 protein could derive from an abnormal shedding of PLAC1 antigen, probably related to an aberrant function of proteolytic enzymes, MMP-2 and/or MMP-9, associated with preeclampsia as previously reported in literature." (PMID 36835024, 2023).